STAT3 (signal transducer and activator of transcription 3)
Diseases named in the same sentence as STAT3 in open-access papers (continued):
Sharing a sentence is not in itself a finding about the gene and the disease.
ischemia (continued). "In cerebral IRI, administration of a ROS scavenger prior to ischemia suppressed STAT3 activation indicating the link between ROS production and STAT3 phosphorylation." (PMID 34948185, 2021). "Using the same animal model, it was reported that STAT3 is essential for the cardioprotective effect of ischemic post-conditioning induced by 3 cycles of IR (10 s ischemia-10 s reperfusion)." (PMID 31709266, 2019). "A significant body of in vivo and in vitro evidence suggests that STAT3 activation results in a cardioprotective response to ischemia and IR injury." (PMID 31709266, 2019). "During ischemia, STAT3 is generally phosphorylated on its Y705 residue with a further increase in phosphorylation of this residue during reperfusion." (PMID 31709266, 2019). "STAT3 is also activated in reactive astrocytes in acute CNS diseases such as ischemia, or spinal cord injury." (PMID 30322407, 2018). "Focal ischemia-induced STAT3 phosphorylation was previously reported to be localized in various cell types including microglia/macrophages, astrocytes and neurons." (PMID 28923114, 2017). "Total STAT3 significantly reduced following ischemia and 1 hour of reperfusion (n = 5, p < 0.01 versus control), but it was induced after 24 hours of reperfusion (n = 5; p < 0.001 versus Control)." (PMID 28373901, 2017). "STAT3 phosphorylation was undetectable pre-ischemia, faint at 0 h, peaked 1 h after reperfusion, and then decreased significantly at 3 h after reperfusion." (PMID 26010537, 2015). "STAT3 knockout animals have revealed the pleiotropic role of STAT3 in many organs and cell types including the heart, skin, T lymphocytes, monocytes/neutrophils, mammary epithelium, liver and neurons following ischemia." (PMID 23759023, 2013). "In present study, the activation of STAT3 in response to ischemia reperfusion injury in optic nerve is prior to the initial react of astrocytes." (PMID 23383263, 2013). "The ratio of p-STAT3 to STAT3 on the ischemia side was much higher than on the control side in the cerebral cortex (p <0.01), hippocampus (p <0.01) and corpus striatum (p <0.05)." (PMID 21957487, 2011). "Our recent study has also demonstrated that acute administration of SDF-1 prior to ischemia protects myocardial function through increased STAT3 activation following I/R injury." (PMID 22195033, 2011). "Within the CNS, the JAK2/STAT3 signaling pathway can be activated in response to stimulus conditions, such as ischemia, trauma, and radiation, and is involved in the regulation of apoptosis, inflammatory responses, vascular remodeling, oxidative stress, and cellular autophagy." (PMID 40406486, 2025). "Iron overload following ischemia may be mediated through two primary pathways: IL-6–JAK/STAT3–hepcidin axis: Ischemia-induced IL-6 activates the JAK/STAT3 signaling pathway, which enhances hepcidin expression." (PMID 41425599, 2025). "In this article, we provide an overview of the Janus kinase–signal transducer and activator of transcription 3 (JAK–STAT3) pathway involved in ischemia/reperfusion injury in the myocardium, which may be activated by the vasospasm-inducing action of the drug." (PMID 39455447, 2024). "Thymosin β4 may protect the myocardium by downregulating STAT1 mRNA expression and upregulating STAT3 mRNA expression and inhibiting myocardial apoptosis induced by ischemia and reperfusion after severe scald injury." (PMID 35281544, 2022). "Thymosin β4 may protect the myocardium by downregulating STAT1 and upregulating STAT3 expression and inhibiting myocardial apoptosis induced by ischemia and reperfusion after severe scald injury." (PMID 35281544, 2022). "The three hub genes, STAT3, NOTCH1, and FOXO3, which are crucial essential factors to regulate the vascular diseases, and closely associated with modulation of proliferation, migration, differentiation and ischemia in a wide range of vascular diseases." (PMID 34988135, 2021).
ischemia (continued). "Furthermore, we found that miR-30b, a molecule which is required for IL-21-induced angiogenesis under ischemia, also increases STAT3 activation with reduced SOCS3 expression." (PMID 35008699, 2021). "We show that STAT3 regulates angiogenic and metabolic pathways before HIF1α, suggesting that HIF1α is not the initiating trans-acting factor in the response of pericytes to ischemia." (PMID 29518129, 2018). "Activation of STAT3 before a lethal ischemia may play a role in the beneficial effect of endotoxin-induced delayed PreC." (PMID 28282895, 2017). "A previous study showed that JAK1 and STAT3 are activated in neurons, astrocytes and microglia after focal cerebral infarction, and may provide neuroprotection in the acute phase of ischemia." (PMID 28542400, 2017). "Previous studies have shown that after focal cerebral infarction, the activation of JAK1 and STAT3 in microglia may provide neuroprotection in the acute phase of ischemia." (PMID 28542400, 2017). "There is a fine balance in the effects of IL-6/STAT3 signaling, since STAT3 activity in acute ischemia is cardioprotective, while continuous activation could be detrimental." (PMID 25997003, 2015). "We also evaluated the effect of NMN upon the activity of Akt, ERK1/2 and STAT-3, well-established mechanisms of cardioprotection, using homogenates obtained from hearts subjected to either 30 minutes of ischemia followed by 1 hour of reperfusion or sham operation." (PMID 24905194, 2014). "The reperfusion injury signaling kinase (RISK) pathway including PI3K/Akt signaling cascade and the protective survivor activating factor enhancement (SAFE) pathway including JAK2/STAT3 signaling cascade are the most important pathways involved in eNOS activation and ischemia myocardial protection." (PMID 21912612, 2011). "In the 4-VO ischemia model (permanent bilateral vertebral artery occlusion and 15-min bilateral carotid artery occlusion), signal transducer and activator of transcription 3 (STAT3) phosphorylation and STAT3 DNA binding activity increased with the reperfusion time until 72 h after reperfusion." (PMID 36142301, 2022). "In future study, two points will still need to be clarified: whether the activation of STAT3 in neurons, reactive astrocytes and microglia would play different roles in ischemia-induced injury and whether STAT3 activation in different brain regions may serve different functions." (PMID 28923114, 2017). "Finally, HDL failed to reduce IS in isolated hearts from TNF-α and STAT-3 deficient mice subjected to ischemia." (PMID 25237809, 2014). "p-Stat3 expression was increased in both Ntg and GET-1 mice in the ischemia brain at 7 days after tMCAO." (PMID 31733648, 2019). "IPC, IPost, and RIPerC differ in their temporal windows and initiating mechanisms.IPC triggers protection before ischemia through early activation of PKC-ε, Akt, ERK1/2, and STAT3, followed by a delayed transcriptional phase involving JAK–STAT and p38 MAPK signaling." (PMID 40885749, 2025). "Its expression is rapidly induced by ischemia–reperfusion injury, promoting leukocyte adhesion to ECs via the Janus kinase 2 (JAK2)-signal transducer and activator of transcription 3 (STAT3) pathway by upregulating vascular cell adhesion molecule-1 (VCAM-1) expression." (PMID 40332339, 2025). "This reduction exacerbates brain injury following ischemia by binding to and enhancing the ubiquitination of STAT3, accelerating the degradation of signal transducer and activator of transcription 3 (STAT3) protein, ultimately triggering apoptotic signaling pathways." (PMID 39606233, 2024). "STAT1, STAT3, and STAT6 are all involved in the activation of microglia induced by ischemia." (PMID 37361996, 2023).
ischemia (continued). "Briefly, our study shows that under hypoxic conditions, the expression of KPNA2 was upregulated in a hindlimb ischemia model and endothelial hypoxia and that the binding of KPNA2 and STAT3 was increased under hypoxic conditions, which promoted angiogenesis under hypoxic conditions." (PMID 36578083, 2022). "The role of mitochondrial STAT3 in ECs following ischemia has not been explored; however, compromised mitochondrial function in cerebrovascular ECs contributes to increased BBB permeability." (PMID 36293020, 2022). "In response to ischemia, the endogenous STAT3 level increases; however, the ischemia-induced increase in STAT3 is not sufficient to protect the mitochondria." (PMID 32121587, 2020). "STAT-3 regulation may affect inflammation during AMI and very recently, the protective role of STAT-3 inhibition was described in a murine model of 30 minutes of ischemia and 24 hours of reperfusion." (PMID 39958474, 2025). "Compared to the vehicle control, in rats treated with AG490, as a JAK2 phosphorylation inhibitor, in the sham group, JAK2 and STAT3 phosphorylation did not occur after ischemia; also, the infarct volume and apoptotic cells were significantly decreased, and neurological deficits were improved." (PMID 37786415, 2022). "Recently, BBR has been reported to inhibit the phosphorylation of JAK/STAT3 signaling without altering the total proteins of JAK2 and STAT3 to protect rat heart from ischemia/reperfusion injury, suggesting that JAK2 may not be the direct target of BBR." (PMID 32213189, 2020). "This protective effect of renalase against ischemia is probably provided by activation of renalase-dependent plasma membrane receptor, PMCA4b, with the final activation of mitogen-activated protein kinase (MAPK) and signal transducer and activator of transcription (STAT3) pathways." (PMID 31737132, 2019).
Hyperglycemia (73 papers, 2010 to 2026). An increased concentration of glucose in the blood. "For instance, it was demonstrated that hyperglycemia was associated with increased adropin expression, as well as the signal transducer and activator of transcription 3 (STAT3) activation in the liver of streptozotocin-induced diabetic rats." (PMID 35955453, 2022). "Recently, numerous studies have implicated the JAK2/STAT3 signaling pathway in the progression of DN and various diabetic characters such as hyperglycemia, angiotensin II, and AGEs can also activate the JAK/STAT pathway." (PMID 34784849, 2021). "The mechanism of cFGF-21 ameliorates hyperglycemia associated with inhibiting hepatic gluconeogenesis by regulation of STAT3 signal pathway and improving pancreatic beta-cell survival." (PMID 27203422, 2016). "By knockdown or inhibition of STAT3, the hyperglycemia related high expression of fibrosis associated targets was reversed." (PMID 27519769, 2016). "The mechanism that cFGF-21 ameliorates hyperglycemia associated with inhibiting hepatic gluconeogenesis by regulation of STAT3 signal pathway and improving pancreatic beta-cell survival." (PMID 27203422, 2016). "Local expression patterns of 8-OHdG, VEGF and p-STAT3 in the initial stage of experimentally induced CNV formation were investigated to determine a potential underlying mechanism for the effects of hyperglycaemia." (PMID 23094067, 2012). "STAT3 activation has been linked to endoplasmic reticulum stress in endothelial cells induced by hyperglycemia and may contribute to vascular injury through the upregulation of inflammation and angiogenesis-related genes like VEGF and HIF-1." (PMID 40066291, 2025). "So at beginning, we speculated that there might be a possible association between the phosphorylation site of STAT3 and the activation modes of IL‐6 signalling, which subsequently plays different roles in podocyte impairment during hyperglycaemia." (PMID 28881473, 2018). "Another study demonstrated that XYS alleviated CUMS-induced depressive symptoms and hyperglycemia by modulating the Leptin Receptor (LepR)-Signal Transducer and Activator of Transcription 3 (STAT3)/PI3K cascade." (PMID 41535967, 2026). "Feeding an HFD to mice with Stat3+/+ myeloid cells led to hyperglycemia, hyperinsulinemia, and an intolerance to both glucose and insulin." (PMID 40801626, 2025). "STAT3 mediates the proliferation of CFs and subsequent collagen synthesis and is involved in hyperglycemia-promoted fibrosis." (PMID 41170186, 2025). "The study unveiled significant amelioration of hepatic SIRT1/STAT3 pathway suppression, hyperglycemia, and hepatic gluconeogenesis by melatonin." (PMID 38690282, 2024). "Hyperglycemia can inhibit STAT3 through C/EBP protein mediated ER stress, thus aggravating liver IRI." (PMID 36761734, 2023). "STAT3 is known to be an upstream regulator of MYC, and its association with hyperglycemia has been reported in the kidneys, lungs, and heart." (PMID 32609742, 2020). "Hyperglycemia strengthened the STAT3 phosphorylation, which was accompanied by elevated MYC expression in Kras-mutant cells." (PMID 32609742, 2020). "Further, hyperglycemia itself can reproduce these effects in keratinocyte cultures where IL-6-induced p-STAT3 levels are increased compared to control." (PMID 31073533, 2019). "Glucose is a critical component of the pro-inflammatory response of macrophages and hyperglycaemia has been shown to induce phosphorylation of STAT3 and secretion of pro-inflammatory cytokines in mouse peritoneal macrophages." (PMID 31287846, 2019). "STAT3 activation is also known to be involved in hyperglycaemia-induced endoplasmic reticulum stress in endothelial cells; inhibiting NOX4 can attenuate high-glucose induced reactive oxygen species (ROS) generation and STAT3 activation." (PMID 31286987, 2019).
Hyperglycemia (continued). "In conclusion, PCr improves mitochondrial functions and exerts an antiapoptotic effect in vivo and in vitro exposed to oxidative stress by hyperglycemia through the JAK2/STAT3 signaling pathway." (PMID 31885809, 2019). "Taken together, our study demonstrated that both the IL‐6 classic signalling and trans‐signalling are activated and play a detrimental role in podocyte injury during hyperglycaemia via STAT3 Tyr 705 phosphorylation." (PMID 28881473, 2018). "STAT3 is the major downstream signalling of IL‐6 and plays an essential role in hyperglycaemia‐initiated glomerular and podocyte injury." (PMID 28881473, 2018). "In recent years, an increasing number of studies have demonstrated that SOCS3 and STAT3 mediate inflammation, apoptosis, and insulin signalling in hyperglycaemia-stimulated retinal endothelial cells." (PMID 29318137, 2017). "To conclude, telmisartan works through PPARδ, instead of the AMPK pathway, to suppress the hyperglycemia-enhanced expression of STAT3/CTGF/MMP9 and the subsequent cardiac fibrosis (Graphic abstract)." (PMID 27519769, 2016). "Our findings in cultured macrophages show that hyperglycemia impacts IL10 signaling at the level of STAT3, a key node in intracellular IL10 signal transduction." (PMID 26883847, 2016). "In conclusion, the mitochondrial complex I protein GRIM-19 can mediate hyperglycemia-induced p-STAT3 signal in both HeLa and H9C2 cell culture." (PMID 27101310, 2016). "Instead, of external inhibition of STAT3, internal knockdown of STAT3 by siRNA also directly reversed the hyperglycemia-related high expression of CTGF, STAT3, and MMP9." (PMID 27519769, 2016). "This activity may be crucial in mice during the postprandial period, when glucose availability can lead to hyperglycemia, highlighting the key role of IL-13 in regulating glucose metabolism via STAT3." (PMID 41007770, 2025). "STAT3 also mediates CF proliferation and collagen synthesis during hyperglycemia-promoted fibrosis." (PMID 41170186, 2025). "Additionally, high glucose regulates hepassocin expression in an HNF1- and STAT3-dependent manner, and serum hepassocin concentrations were significantly decreased after treatment of hyperglycemia in patients with hyperglycemic crisis." (PMID 37509575, 2023). "In renal mesangial cells, hyperglycemia was shown to enhance the activation of STAT3." (PMID 32609742, 2020). "Thus, the HO-1/STAT3 signaling pathway plays a major role in mediating cellular protection and improving cardiac function under conditions of hyperglycemia." (PMID 31527528, 2019). "Interestingly, we found that hyperglycemia inhibited IL-10-secreting M2-like macrophage polarization, as revealed by decreased Arg1 and Mrc1 gene induction accompanied by a decrease in STAT3 and STAT6 signaling pathway activation." (PMID 29081777, 2017). "Telmisartan improved the hyperglycemia-induced cardiac fibrosis through the PPARδ/STAT3 pathway." (PMID 27519769, 2016). "However, in contrast to above finding, we found that the overexpression of STAT3 directly downregulated PPARδ independent from the stimulation of hyperglycemia." (PMID 27519769, 2016). "Our findings demonstrate that hepatic IL-6/STAT3 signaling also contributes to maintaining metabolic homeostasis in the face of an intestinal microbiome that can induce mature-onset body fat accumulation and hyperglycemia when IL-6 trans-signaling is inhibited." (PMID 41362820, 2026). "Metformin may modulate inflammation by ameliorating hyperglycemia and through an 5’ adenosine monophosphate-activated protein kinase-dependent modulation of the mammalian target of rapamycin and the signal transducer and activator of transcription 3 and 5 of T-cells." (PMID 36277720, 2022).